ZC3H7A (zinc finger CCCH-type containing 7A)
Description:
May be a specific regulator of miRNA biogenesis. Binds to microRNAs MIR7-1, MIR16-2 and MIR29A hairpins recognizing the 3'-ATA(A/T)-5' motif in the apical loop.
Synonyms: ZC3H7; ZC3HDC7; HSPC055; FLJ20318
Tractability: PROTAC: ubiquitination databases record sites on it; its protein half-life has been measured.
Gene: Protein-coding gene on chromosome 16 (11,750,586 to 11,797,258, reverse strand). Ensembl gene ENSG00000122299.
Subcellular location: Nucleus
Subcellular location (Human Protein Atlas): Cytosol
Gene Ontology:
Molecular function: miRNA binding; RNA binding; metal ion binding
Biological process: miRNA processing; post-transcriptional regulation of gene expression
Cellular component: cytosol; nucleus
Genetic constraint (gnomAD): Loss-of-function variants: 41 observed, 115.01 expected, observed/expected ratio (o/e) 0.36, 90% interval 0.28 to 0.46. The upper end of that interval is the gene's LOEUF score, 0.46, which puts it in group 2 of 6, group 1 being the genes least tolerant of losing a copy. Missense variants: 911 observed, 1,107.7 expected, observed/expected ratio (o/e) 0.82, 90% interval 0.78 to 0.87. Synonymous variants: 375 observed, 377.33 expected, observed/expected ratio (o/e) 0.99, 90% interval 0.91 to 1.08.
Homologues: Orthologues: chimpanzee ZC3H7A (99% identical), macaque ZC3H7A (99% identical), dog ZC3H7A (94% identical), pig ZC3H7A (92% identical), rabbit ZC3H7A (92% identical), guinea pig ZC3H7A (87% identical), rat Zc3h7a (86% identical), mouse Zc3h7a (85% identical), tropical clawed frog zc3h7a (54% identical), zebrafish zc3h7a (53% identical). Paralogues in human: ZC3H7B (46% identical).
Diseases named in the same sentence as ZC3H7A in open-access papers:
ZC3H7A is named in the same sentence as 3 diseases in open-access papers, as found by Europe PMC text mining. Sharing a sentence is not in itself a finding about the gene and the disease. The quoted sentences say what the papers report.
viral infections (1 paper, 2026). "Long noncoding ZC3H7A (LncZC3H7A), which has been suggested to be transcriptionally co-regulated with ZC3H7A expression, facilitated elevated levels of type I IFN in response to viral infections." (PMID 41139700, 2026).
cancer (1 paper, 2023). A tumor composed of atypical neoplastic, often pleomorphic cells that invade other tissues. "Interestingly, most of these genes are linked with cancer processes (Pld1, Fam13c, Svbp, TMem192, Zc3h7a, RTP4, Naa30, Zgrf1, Slc33a1, Dnmt3b, Map6, Plin4, Eps8L2, Alg12, Capg and Tdp2)." (PMID 37700325, 2023).
ZC3H7A also shares sentences with these, for which no sentence is quoted: endometrial stromal sarcomas (3 papers).